TRAF6 (TNF receptor associated factor 6)
Diseases named in the same sentence as TRAF6 in open-access papers (continued):
Sharing a sentence is not in itself a finding about the gene and the disease.
myeloid malignancies (6 papers, 2013 to 2026). "TNF receptor associated factor 6 (TRAF6) is an E3 ubiquitin ligase that has been implicated in myeloid malignancies." (PMID 38609495, 2024). "Further investigation indicated TRAF6 mediates ubiquitination of MYC protein and plays a role of tumor suppressor in myeloid neoplasms, suggesting the decreasing gradient of TRAF6 expression was related to leukemic transformation risk." (PMID 37953918, 2023). "In patients with myeloid malignancies, TRAF6 inhibition has been observed, suggesting its potential contribution to the onset of acute leukemia." (PMID 38169510, 2024). "In conclusion, TRAF6 plays a significant role in myeloid neoplasms, impacting signaling pathways and ubiquitination processes." (PMID 38169510, 2024). "Critically, the repression of TRAF6 has been observed in a subset of patients with myeloid malignancy, suggesting that dysregulation of TRAF6 can lead to acute leukemia." (PMID 36434065, 2023). "Conversely, TRAF6’s tumor suppressive function is evident in different models of myeloid neoplasms." (PMID 38609495, 2024).
myocardial inflammation (6 papers, 2020 to 2024). "For instance, miR-23b-5p targets TRAF6 to inhibit cell apoptosis and alleviate myocardial inflammation, while miR-615 can suppress the PI3K-AKT pathway, influencing the apoptosis of hippocampal neurons." (PMID 38105181, 2023). "Excessive activation of TLR4/IRAK1/TRAF6/NF-κB pathway commonly exists in myocardial inflammation." (PMID 36148071, 2022). "Therefore, down‐regulation of MEG3 alleviated myocarditis by up‐regulating miR‐223 and inhibiting TRAF6." (PMID 33047847, 2020). "Based on the finding that MEG3 regulates TRAF6 by binding to miR‐223, we wished to explore whether miR‐233 and TRAF6 are involved in the mediation of myocarditis by MEG3." (PMID 33047847, 2020). "In this study, we constructed a VMC model by infecting mice with CVB3, and then showed that inhibition of MEG3 could suppress the NF‐κB pathway as well as increase M2 macrophage transition through miR‐223‐mediated down‐regulation of TRAF6, therefore, ameliorating myocarditis in the VMC mice." (PMID 33047847, 2020). "Potential targets of miR-146a are TLR3, TRAF6 and IRAK1/2/4; however, TLR3 and TRAF6 have recently been shown to be relevant to myocarditis." (PMID 39456716, 2024). "Down‐regulations of MEG3 or TRAF6 or up‐regulation of miR‐223 was observed to increase mouse weight, survival rate, LVEF and LVFS, while inhibiting myocarditis and inflammation via the NF‐κB pathway inactivation in VMC mice." (PMID 33047847, 2020). "Meanwhile, following miR‐223 up‐regulation or TRAF6 down‐regulation, expression of NLRP3 inflammasome‐related components (NLRP3, ASC and Caspase‐1) was reduced, mouse body weight was elevated, survival rate was increased, myocarditis was inhibited in mice, and LVEF and LVFS rose in VMC mice." (PMID 33047847, 2020).
oral cancer (6 papers, 2013 to 2022). "We demonstrated that the TRAF6 expression level in the 3 human oral cancer cell lines was higher than in hNOK, a human normal oral keratinocytes cells." (PMID 29703234, 2018). "We observed increased TRAF6 levels in the 3 human oral cancer cell lines compared with the hNOK cells." (PMID 29703234, 2018). "We analyzed the basal expression levels of TRAF6 in human oral keratinocyte (hNOK) cells and 3 human oral cancer cell lines." (PMID 29703234, 2018). "TRAF6 played an oncogenic role in tumorigenesis of human oral cancer cells and oral tumor growth was suppressed by bortezomib and IR treatment." (PMID 29703234, 2018). "We utilized TRAF6 shRNA to inhibit TRAF6 expression in human oral cancer cells." (PMID 29703234, 2018). "Our results also indicate that a combination of proteasome inhibitor with IR treatment and TRAF6 inhibition may be a potential therapeutic strategy for the treatment of oral cancer." (PMID 29703234, 2018). "In addition, the combined treatment enhanced the therapeutic efficacy of oral cancer cell lines by downregulating the TRAF6-Akt signaling pathway." (PMID 29703234, 2018). "TRAF6 could be a promising target for therapeutic strategies against oral cancer." (PMID 29703234, 2018). "In addition, the clinical impact of TRAF6 in oral cancer patients was also investigated." (PMID 29703234, 2018). "However, the clinical impact of TRAF6 in oral cancer patients has seldom being investigated." (PMID 29703234, 2018).
ovarian carcinoma (6 papers, 2007 to 2023). A malignant neoplasm originating from the surface ovarian epithelium. "In contrast, depletion of TRIP6 by TRIP6-specific shRNA or Cas9/sgRNA greatly enhances the association of TRAF6 with A20 and CYLD, and attenuates lysophosphatidic acid-induced muclear factor-κB and JNK/p38 activation in ovarian cancer cells." (PMID 27134758, 2016). "Previous studies have demonstrated that miR-146b could induce cell apoptosis via TRAF6 and IRAK120; thus, we investigated whether miR-146b overexpression in ovarian cancer cells also caused apoptosis." (PMID 30409964, 2018). "Indeed, under physiological conditions, TRIP6 bound to TRAF6 constitutively in SKOV-3 ovarian cancer cells that express TRIP6 and the LPA2 receptor at high levels." (PMID 27134758, 2016). "Nonetheless, depletion of TRIP6 by either shRNA or Cas9/sgRNA not only enhanced the association of TRAF6 with A20, but also with CYLD in untreated and treated cells, suggesting a significant role for TRIP6 in antagonizing the binding of TRAF6 to both A20 and CYLD in ovarian cancer cells." (PMID 27134758, 2016). "We found that miR-146b did not regulate the expression levels of TRAF6 and NF-ᴋB in the ovarian cancer cell lines." (PMID 34369236, 2021).
Parkinson disease (6 papers, 2013 to 2025). A progressive degenerative disorder of the central nervous system characterized by loss of dopamine producing neurons in the substantia nigra and the presence of Lewy bodies in the substantia nigra and locus coeruleus. "Studies in animal models of Parkinson’s disease have also found that activation of the Toll-like receptor 4/TNF receptor-associated factor 6 (TRAF6)-mediated MAPK signaling pathway is involved in neuroinflammatory processes." (PMID 37207228, 2023). "Interestingly, recent evidence implicates the E3 ligase activity of TRAF6 in the pathogenic aggregation of mutant proteins in neurodegenerative diseases such as Parkinson’s disease and Huntington disease." (PMID 23758787, 2013). "Interestingly, tumor necrosis factor receptor-associated factor 6 (TRAF6)-mediated K27-linked ubiquitination has been shown to modify proteins such as α-synuclein and DJ-1 in Parkinson’s disease and huntingtin in Huntington’s disease, suggesting a role in neurodegenerative diseases." (PMID 40307574, 2025). "TRAF6 is an ubiquitin ligase that has been shown to bind misfolded proteins and promote accumulation of protein aggregates in patients with Parkinson’s disease." (PMID 24170811, 2014). "It was found that TRAF6 binds to misfolded mutant DJ-1, aSYN and N-HTT, proteins involved in the pathogenesis of the Parkinson’s disease and Huntington disease." (PMID 23758787, 2013).
tuberculosis (6 papers, 2016 to 2026). A chronic, recurrent infection caused by the bacterium Mycobacterium tuberculosis. "Furthermore, Rv2626c, a promising vaccine candidate of tuberculosis, directly bound to TRAF6 and inhibited K63-linked polyubiquitination in TRAF6." (PMID 35572598, 2022). "Therefore, we demonstrated a novel role of miR-146a in the modulation of host defense against mycobacterial infection by repressing NO production via targeting TRAF6, which may provide a promising therapeutic target for tuberculosis." (PMID 27025258, 2016).
acute pancreatitis (5 papers, 2018 to 2025). An acute inflammatory process that leads to necrosis of the pancreatic parenchyma. "A previous study showed that the down-regulation of TRAF6 is associated with the progression of acute pancreatitis with a complication of lung injury in mice." (PMID 30271405, 2018). "MiR‐146a alleviates acute pancreatitis in mice by targeting TRAF6 and suppressing the activation of the NF‐κB signaling pathway." (PMID 40018991, 2025). "TRAF6 has also demonstrated a protective role in the progression of acute pancreatitis in acinar cells as stimulation of TLR4 lead to increased SOCS1 and SOCS3 expression, which are responsible for the degradation of TRAF6 through polyubiquitination." (PMID 38585277, 2024).
Cerebral ischemia (5 papers, 2017 to 2023). Restriction of arterial blood supply to the brain associated with insufficient oxygenation to support the metabolic requirements of the tissue. "The expression of TNF receptor-associated factor-6 (TRAF6) was markedly increased after cerebral ischemia in mice." (PMID 33071819, 2020). "In our present study, we found that geniposide inhibited the expression of TRAF6 and the activation of NF-κB after cerebral ischemia." (PMID 37333874, 2023). "The ubiquitin E3 ligase TRAF6 promotes cerebral ischemia-reperfusion injury through increased ubiquitination and activation of Rac1." (PMID 33609088, 2021).
cognitive decline (5 papers, 2023 to 2025). "Lastly, TRAF6 plays a significant role in the central nervous system, and is related to AD through its induction of Ab-induced neurotoxicity and cognitive decline." (PMID 39979805, 2025). "As to POCD, miR-146a is reported to be associated with cognitive decline by suppressing hippocampal neuroinflammation in mice, via regulation of the IRAK1/TRAF6/NF-κB pathway." (PMID 40718798, 2025). "It is found that IL-17 is increased in APP/PS1 mice and Aβ-induced model mice and leads to neurotoxicity and cognitive decline through the IL-17/TRAF6/NF-κB pathway." (PMID 37441611, 2023). "Inhibition of IL-17 could ameliorate Aβ-induced neurotoxicity and cognitive decline in C57BL/6 mice by downregulating the TRAF6/NF-κB pathway, which provides new clues for the mechanism of Aβ-induced cognitive impairments." (PMID 36823558, 2023).
depression (5 papers, 2012 to 2025). "Collectively, these findings provide convincing evidence to indicate that BDD containing ACT and FA restores activated microglial homeostasis mediated via the Th17 cell‐driven RORγt/Act1/TRAF6 signaling pathway to ameliorate chronic stress‐induced depression." (PMID 40832701, 2025). "The best model predicting treatment-related depression included expression levels of TRAF6 and TGF-β1 with a P-value of 0.001185, a sensitivity of 63.16% (38.4–83.7%), a specificity of 87.88% (71.8–96.6%), and an area under the curve (AUC) of 0.748 (0.608–0.858)." (PMID 23139898, 2012). "Our results showed that the expression levels of TLR4, MyD88, NF-κB-p65, TAK1, IRAK1, TRAF6, inflammasome-related NLRP3, ASC, and caspase-1 were all increased in rats of the depression model group." (PMID 33505499, 2021).
HIV-1 infection (5 papers, 2011 to 2025). The type species of lentivirus and the etiologic agent of acquired immunodeficiency syndrome (AIDS). "Interestingly, TRAF6 knockdown in SAMHD1-deficient cells significantly inhibited HIV-1 infection and activation of NF-κB induced by virus infection." (PMID 33177202, 2021). "We report that HIV-1 infection of primary human macrophages decreases tumor necrosis factor receptor-associated factor 6 (TRAF6) and virus-induced signaling adaptor (VISA) expression, which are both components of the IFN signaling pathway controlling viral replication." (PMID 22140520, 2011). "While these observations are provocative, the mechanism of how TRAF6 promotes HIV-1 infection is unclear." (PMID 38241362, 2024). "The knockdown of TRAF6 inhibits HIV-1 infection, suggesting that it is a host dependency factor; moreover, TRAF6 mRNA increases in HIV-1–infected MT2 cells." (PMID 38241362, 2024). "Yet, SERINC5 has been shown to enhance MDA5-mediated IFN signaling, and SERINC5 can interact with MAVS and TRAF6 to inhibit HIV-1 infection." (PMID 36223419, 2022). "We present evidence that TRAF6, important for transcriptional regulation of the interferon pathway, is affected early in the process of HIV-1 infection of primary human macrophages." (PMID 22140520, 2011). "HIV-1 infection reduced TRAF6 gene expression with the resulting enhanced viral replication." (PMID 22140520, 2011). "Indeed, TRAF6 KD reduced HIV-1 infection at 24 hpi by ∼2-fold in both SAMHD1 KO and control cells." (PMID 33177202, 2021). "Furthermore, TRAF6 has been shown to regulate HIV-1 production in macrophages and knockout of microRNA-146a, which targets TRAF6 and reduces HIV-1 infection and reactivation of latently infected cells, providing further evidence that TRAF6 plays an important role in HIV-1 infection." (PMID 33177202, 2021). "To analyze the impact of TRAF6 and VISA in the context of HIV-1 infection, we suppressed both genes independently using siRNA." (PMID 22140520, 2011). "In contrast, TRAF6 KD reduced viral luc mRNA by 3-fold in SAMHD1 KO and by 2-fold in control cells, suggesting that TRAF6 is an important cellular component for HIV-1 infection at a replication stage between late RT and mRNA transcription." (PMID 33177202, 2021).
Insulin resistance (5 papers, 2011 to 2025). Increased resistance towards insulin, that is, diminished effectiveness of insulin in reducing blood glucose levels. "The TLRs, IRAK1, and TRAF6 have been shown to be involved in innate immunity and the induction of metabolic syndromes such as insulin resistance and T2D." (PMID 37623520, 2023). "The reduced level of miR-124 could promote progression to T2DM through interactions with NF-κB, TRAF-6, and cytokines (TNFα and IL-6), which lead to insulin resistance, poor glycemic control, and a pro-inflammatory state." (PMID 37628595, 2023).
liver cancer (5 papers, 2017 to 2025). An epithelial or non-epithelial malignant neoplasm that arises from the liver. "Meanwhile, USP8 regulated liver cancer cell progression via inhibition of TRAF6-mediated signaling." (PMID 36539510, 2023). "Using The Cancer Genome Atlas datasets to re-analyze the effect of some previously reported metastatic genes-e.g., JAM2, PPARGC1A, SIK2, and TRAF6-on overall survival of patients with renal and liver cancers, we found that these genes are actually protective factors for patients with cancer." (PMID 28372569, 2017). "Cyld negatively regulates NF-kB, known to be one of the most important players in inflammation and liver cancer, and the MAPK signaling cascade by removing ubiquitin chains from signaling molecules, such as NEMO, TRAF2, TRAF6, TRAF7, TAK1 and RIP1." (PMID 37298191, 2023). "Notably, the expression of SNHG16 is significantly elevated in liver cancer tissues and cell lines, where it exerts oncogenic effects through pathways such as miR-17-5p/p62, miR-4500/STAT3, and miR-605-3p/TRAF6/NF-κB." (PMID 40427707, 2025). "Notably, TRAF6‐dependent phosphorylation of ERK1/2 induces upregulation of MCL‐1, ultimately suppressing apoptosis in liver cancer cells." (PMID 37484971, 2023).
lung adenocarcinoma (5 papers, 2020 to 2023). A carcinoma that arises from the lung and is characterized by the presence of malignant glandular epithelial cells. "One study showed that sodium butyrate affects proliferation and migration of A549 cells by activating the TNF receptor-associated factor 6 (TRAF6)-thioredoxin-interacting protein (TXNIP) pathway, suggesting that sodium butyrate has an effective therapeutic effect on lung adenocarcinoma." (PMID 37180438, 2023). "A lower expression of TRAF6 was revealed in both lung squamous cell carcinoma (LUSC) and lung adenocarcinoma (LUAD) than in adjacent normal lung tissues." (PMID 33015045, 2020).
anaplastic thyroid cancer (4 papers, 2021 to 2024). "Emodin also demonstrated in vitro and in vivo suppressive effects against anaplastic thyroid cancer by affecting TRAF6-mediated pathways." (PMID 38667760, 2024). "Emodin can inhibit angiogenesis and metastasis in anaplastic thyroid cancer (ATC) by inhibiting the TRAF6/HIF-1α/VEGF and TRAF6/CD147/MMP9 signaling pathways." (PMID 35637953, 2022). "Besides blocking angiogenesis by inhibiting the TRAF6/HIF-1α/VEGF pathway in 8505c and SW1736 cells, 37 also suppressed anaplastic thyroid cancer metastasis by inhibiting the TRAF6/CD147/MMP9 pathway." (PMID 38667760, 2024). "Adequate emodin treatment inhibited both TRAF6/HIF-1α/VEGF and TRAF6/CD147/MMP9 axes to block cell metastasis and angiogenesis in human anaplastic thyroid cancer cell lines in vitro and in vivo." (PMID 38540100, 2024). "Emodin (less than 40 μM) dose-dependently suppressed both TRAF6/HIF-1α/VEGF and TRAF6/CD147/MMP9 signaling pathways to simultaneously inhibit pro-angiogenesis and invasion capacity of human anaplastic thyroid cancer cell lines (8505c and SW1736)." (PMID 34629100, 2021).
co-infection (4 papers, 2019 to 2025). "Another study found that PDCoV and PEDV co-infection regulated pro-inflammatory cytokines through the TRAF6-mediated canonical NF-κB and IRF7 signaling pathways, leading to enhanced viral evasion of the mucosal innate immune response." (PMID 40943649, 2025). "Meanwhile, single-PDCoV infection and PDCoV/PEDV co-infection regulate proinflammatory and regulatory cytokines through TRAF6-mediated canonical NF-κB and IRF7 signaling pathways through TLRs." (PMID 36376395, 2022). "The protein expressions of CIKS and TRAF6 were significantly (p < 0.05) upregulated in the co-infection group compared to the MG and E. coli groups." (PMID 31803158, 2019). "The expression of IL-17C, CIKS, TRAF6, NFκB, C/EBPβ, and inflammatory chemokines were significantly up-regulated in response to co-infection." (PMID 31803158, 2019). "Distinctly, VL1 patient, that has disorganized spleen and VL-HIV coinfection was related to SOD1, STAT3, STAT4, ICOS, TRAF6 and IRF3 genes, and CD8+ cells in the RP and expression of IL6 in both regions of spleen." (PMID 38843306, 2024).
dermatitis (4 papers, 2013 to 2025). An inflammatory process affecting the skin. "Surprisingly, similar to CD4Cre-TRAF6-cKO mice, dermatitis, splenomegaly, and lymph node (LN) swelling were observed in Treg-specific TRAF6 cKO mice, and these appeared in all the mice until they were 3 months of age." (PMID 24058613, 2013). "For example, the severe skin inflammation and hyperkeratosis observed in TRAF6[L74H] mice has not been reported in mice with a specific knock-out of TRAF6 in Tregs or all T cells." (PMID 35157702, 2022).
diabetic retinopathy (4 papers, 2015 to 2024). "Another study reported upregulation of CD40, TRAF2, and TRAF6 in patients with diabetic retinopathy, where CD40 was associated with the expression of pro-inflammatory molecules such as intercellular adhesion molecule 1 (CD54), CCL2, and TNFα." (PMID 38554187, 2024). "We hypothesized that the CD40-TNF Receptor Associated Factor 6 (TRAF6) axis plays a pivotal role in the onset of diabetic retinopathy, and that the CD40-TRAF6 axis would be a prime therapeutic target for early-stage non-proliferative diabetic retinopathy." (PMID 36309487, 2022). "However, TRAF6 induced inflammation in human retinal microvascular endothelial cells and human alveolar epithelial cells; loss of TRAF6 effectively relieved inflammation and prevented the development of diabetic retinopathy and LPS-induced acute lung injury." (PMID 38995476, 2024).